ALB (albumin)
Diseases named in the same sentence as ALB in open-access papers (continued):
Sharing a sentence is not in itself a finding about the gene and the disease.
breast carcinoma (continued). "The proposed assumption is consistent with data on the maximum decrease in albumin in breast cancer, an increase in the concentration of α-AAs and the activity of aminotransferases, which are involved in the redistribution of nitrogen in the body." (PMID 39452912, 2024). "Combined therapy using neratinib and silibinin administered via albumin-based nanocarriers was also explored to target breast cancer." (PMID 39456987, 2024). "The uptake of EVs loaded with albumin in macrophage cells and breast cancer cells indicates an efficient and uniform uptake of albumin by the cells." (PMID 39057100, 2024). "Curcumin–human serum albumin nanoparticles decorated with PDL1-binding peptide were used for targeting PDL1-expressing breast cancer cells." (PMID 38258090, 2024). "This study aimed to retrospectively analyse the pathological response and safety of combining albumin-bound paclitaxel (nab-paclitaxel) or docetaxel with anti-HER2 therapy as a neoadjuvant treatment for HER2-positive breast cancer." (PMID 39234401, 2024). "Tracing the nodular involvement of breast cancer patients requires radiation source Tc99m labeled with colloidal albumin to be injected at the tumor site." (PMID 38765148, 2024). "There are several things that can explain why the PNI score, which consists of serum albumin and total lymphocyte count, can be used to predict the prognosis of cancer, including breast cancer." (PMID 38169970, 2024). "In a large retrospective study investigating the nutritional status of breast cancer via albumin and BMI composing the Nutritional Risk Index (NRI), decreased NRI was confirmed to be related to worse OS in early breast cancer." (PMID 38813321, 2024). "Aptamer-functionalized curcumin-loaded human serum albumin (HSA) nanoparticles were employed for targeted delivery to HER2-positive breast cancer cells." (PMID 38258090, 2024). "Albumin-conjugated doxorubicin nanocomposites were studied to overcome the multidrug resistance of breast cancer cells." (PMID 39456987, 2024). "Serum albumin has been described as an independent unfavorable factor for survival in patients with lung, gastric, colorectal, pancreatic, and breast cancer." (PMID 38438901, 2024). "In summary, the developed albumin multifunctional nanoplatform enabled dual enhanced photodynamic immunotherapy for breast cancer via hypoxia-activated chemotherapy." (PMID 39070787, 2024). "CEUS using 25% albumin as a UCA was performed in 23 breast cancer patients, and enhanced LNs were identified in all." (PMID 37423960, 2024). "Previous studies have reported that pretreatment serum ALB can be used as a prognostic indicator in several kinds of cancers, including lung, pancreatic, gastrointestinal, ovarian, and breast cancer." (PMID 38274836, 2023). "In 2005, the FDA approved the use of an albumin-based nanoparticle in nanomedicines for the chemotherapy treatment of breast cancer." (PMID 37836018, 2023). "We attempted to explore the association between a novel albumin-related nutrition marker called “lymphocyte × albumin (LA)” and disease-free survival (DFS) in breast cancer patients undergoing neoadjuvant chemotherapy (NAC)." (PMID 37836576, 2023). "Studies indicate that a decreased serum albumin level, a protein encoded by the ALB gene, is related to shorter survival in breast cancer patients, while high levels reduced the risk of death by 45%." (PMID 36982287, 2023). "Here, the efficiency of the chemo-photothermal and photoacoustic properties of hybrid albumin-modified nanoparticles (HSA-NPs) loaded with doxorubicin was evaluated in a three-dimensional breast cancer cell model." (PMID 38139203, 2023). "This approach has previously been proposed for sentinel LNs mapping in breast cancer treatment indicating that the albumin mixture can be used to enhance ICG intensity." (PMID 37696910, 2023).
breast carcinoma (continued). "In this study, a first-time attempt at combined synthesis of albumin visnagin nanoparticles to assess their synergism for the inhibition of breast cancer cells has been performed." (PMID 37049991, 2023). "According to the xiantao database, COL1A2, COL3A1, FGA, LUM, APOA1, APOH, and COL5A2 were more highly expressed in breast cancer than in normal tissues (p < 0.05), while the opposite pattern was seen for ALB and FBN1 (p < 0.05)." (PMID 37079213, 2023). "In vivo, PFD alone exerted a milder but significant anti‐tumour effect than the chemotherapy drug nanoparticle albumin‐bound paclitaxel (nab‐PTX) did in the breast cancer xenograft mouse model." (PMID 36651490, 2023). "A recently published article discusses using albumin nanoparticles for administering chemotherapeutic drugs in breast cancer therapy, exploring various multifunctional theranostics." (PMID 37836018, 2023). "In the treatment of breast cancer, the uptake of certain drugs, such as albumin-paclitaxel and trastuzumab-metan conjugate (T-DM1), depends on Cav-1-mediated selective endocytosis." (PMID 37828916, 2023). "Paclitaxel (PTX) is a commonly used chemotherapy drug for breast cancer, and the effect is affected by poor water solubility; thus, albumin-bound PTX is the common dosage form in the clinic to improve its water solubility." (PMID 36678653, 2022). "The combination of Gemcitabine plus nanoparticle albumin-bound (nab)-Paclitaxel (GA) have been evaluated as first line regimens for both metastatic pancreatic adenocarcinoma and breast cancer." (PMID 35813042, 2022). "The mean values regarding the ALT, blood urea, creatinine, albumin, and globulin levels were significantly increased in the breast cancer group compared to the control group." (PMID 36558514, 2022). "Serum ALB, a common indicator of nutritional status, is related to the immune status and prognosis of breast cancer." (PMID 35774393, 2022). "It is worth noting that incorporation of Nintedanib into folic acid modified albumin microspheres resulted in an enhanced uptake of the drug into MCF-7 breast cancer cells coupled with higher inhibition rate." (PMID 35126516, 2022). "In in vitro assays, the Al-ProD efficiently bound to three types of albumin (HSA, BSA, MSA) and induced 30-fold strong cytotoxicity in cathepsin B-overexpressed MDA-MB231 breast cancer cells compared to cathepsin B-deficient H9C2 cardiomyocytes." (PMID 35456562, 2022). "This study was determined to evaluate the prognostic value of neutrophil-to-lymphocyte ratio (NLR) and C-reactive protein/albumin ratio (CAR) prior to surgery in luminal breast cancers (BC) with HER2-negativity." (PMID 35317078, 2022). "At the preclinical investigation, numerous albumin-based nanoparticle formulations have been developed for breast cancer therapy, especially in TNBC with promising results." (PMID 35267507, 2022). "A 67-year-old woman with advanced breast cancer (cT4bN1M1, cStage IV) was treated with atezolizumab and nanoparticle albumin-bound (nab) paclitaxel." (PMID 35800819, 2022). "Clinicopathological characteristics of breast cancers according to neutrophil-to-lymphocyte ratio (NLR) or c-reactive protein/albumin ratio (CAR) levels." (PMID 35317078, 2022). "In another clinical trial, albumin nanoparticles bound with rapamycin were used to treat recurrent breast cancer and showed therapeutic efficacy with a 5-year patient survival rate." (PMID 35495618, 2022). "Recently, we developed hybrid eumelanin–silver NPs (MelaSil_Ag) functionalized with human serum albumin (HSA) as a new kind of nanoprobe (MelaSil_Ag-HSA NPs) able to target breast cancer cells via HSA–SPARC interaction." (PMID 34681890, 2021). "One of the current applications that uses nanotechnology in cancer treatments is the development of FDA-approved nanoparticle-bound albumin for breast cancer, pancreatic cancer, and NSCLC." (PMID 33503889, 2021).
breast carcinoma (continued). "Nanoparticle albumin-bound paclitaxel (nab-PTX) is a solvent-free form of paclitaxel used for the treatment of malignant tumors such as breast cancer, lung cancer, and pancreatic cancer." (PMID 34284818, 2021). "Treatment using TLR-7 agonist, imiquimod and systemic albumin bound paclitaxel for recurrent chest wall lesion in breast cancer is effective in inducing disease regressing with a response rate of 20–30%." (PMID 34680503, 2021). "Three taxane-based reagents are widely used as first-line treatment for patients with breast cancer, that is, paclitaxel formulated with either CrEL (Taxol) or solvent-free, albumin nanoparticles (Abraxane) and docetaxel formulated with polysorbate (Taxotere)." (PMID 34646996, 2021). "With regard to MDA-MB-231, albumin-coated AgNPs have shown good activity against this type of breast cancer cells both in vitro and in vivo." (PMID 34834261, 2021). "For example, a folic acid-modified targeting-drug delivery system based on bovine serum albumin nanoparticles achieved targeted accumulation of drugs at the cancer focus that significantly increased anti-cancer effectiveness of Rg5 in breast cancer." (PMID 35002732, 2021). "Since nab-paclitaxel (Abraxane®) has also been effectively used in the chemotherapy of breast cancer in clinical situations, the therapeutic potential of paclitaxel-loaded albumin-encapsulated liposomes has been examined." (PMID 33810483, 2021). "For example, albumin paclitaxel has been widely used clinically, and it can be injected once a week or a month in the treatment of breast cancer or lung cancer." (PMID 34869036, 2021). "Nanoparticle albumin-bound paclitaxel (nab-PTX) has exhibited clinical efficacy in breast cancer treatment, but toxicities can be yielded more at the same time." (PMID 33607781, 2021). "In a recent study, berberine was encapsulated in bovine serum albumin (BSA) nanoparticles (BB-BSA NPs) as a novel nanocarrier for breast cancer treatment." (PMID 34771481, 2021). "Herein, we have developed a nanocarrier system based on albumin, which selectively affects the tumor cells, and hence can revolutionize breast cancer therapy." (PMID 34208533, 2021). "Here we report a 45-year-old woman with breast cancer who developed CME after several months of treatment with albumin-bound paclitaxel (nab-paclitaxel)." (PMID 34966680, 2021). "Albumin-encapsulated liposomes were developed to deliver drugs to solid tumors, such as melanoma, breast cancer, pancreatic ductal adenocarcinoma, and pancreatic cancer." (PMID 33810483, 2021). "The paclitaxel-bound albumin nanocomplex has a diameter of around 130 nm and is one of the best-selling anticancer drugs in the market for breast cancer." (PMID 33503889, 2021). "The 2S albumin from seeds of pumkin showed the cytotoxicity against the breast cancer cell line MCF-7, ovarian teratocarcinoma cell line PA-1, prostate cancer cell line PC-3 and DU-145 and liver hepatocellular carcinoma (Hep G2)." (PMID 34911985, 2021). "Nanoparticle albumin-bound paclitaxel (nab-paclitaxel) as neoadjuvant chemotherapy (NAC) for breast cancer remains controversial." (PMID 35087749, 2021). "Nanomedicine formulations include, among others, Doxil® and Myocet® (liposomal doxorubicin) and Abraxane® (albumin nanoparticle of paclitaxel), indicated to treat advanced-stage breast cancer." (PMID 34207832, 2021). "Ruttala and Ko reported that paclitaxel-loaded albumin nanoparticle-encapsulated liposomes exerted an increased cytotoxicity against 2D-cultured MCF-7 breast cancer cells compared to paclitaxel-loaded albumin nanoparticles." (PMID 33810483, 2021). "For example, salvianolic acid B was reported to ameliorate lipopolysaccharide-induced albumin leakage from rat mesenteric venules by binding to Src, Astragaloside IV was shown to enhance taxol chemosensitivity of breast cancer by targeting caveolin-1." (PMID 34975519, 2021).
breast carcinoma (continued). "Co-encapsulation of CCM and doxorubicin (DOX) in albumin NPs was tested on MCF-7 resistant breast cancer cells." (PMID 31858848, 2020). "Plasma albumin to fibrinogen ratio is involved in human cancer, but its prognostic significance in breast cancer is controversy." (PMID 32590741, 2020). "Among them, CCNE1 and KRT20 were of high expression in BRCA1/2-mutant breast cancer, and ALB and MYOM2 were of low expression." (PMID 31998560, 2020). "One is Abraxane (Celgene), an albumin-bound paclitaxel nanoparticle that is used to treat breast cancer, NSCLC, and pancreatic cancer." (PMID 32610448, 2020). "The dosage (10 mg/kg of body weight) of Au@HSANP used in pharmacokinetic, biodistribution studies and microSPECT imaging was based on the dosage of nab-paclitaxel, an albumin-bound 130-nm nanoparticle form of paclitaxel, for breast cancer treatment." (PMID 30626093, 2019). "Serum albumin has been found to be an independent predictor of prognosis in several studies of patients with malignant tumors, including breast cancer." (PMID 32083015, 2019). "Previous studies have also found that circulating albumin has specific anti-tumor effects on breast cancer." (PMID 32083015, 2019). "Systemic inflammatory markers such as C-reactive protein (CRP), fibrinogen, ferritin, albumin, transferrin, and blood leukocyte components like neutrophils and lymphocytes are associated with prognosis of RCC, colorectal, and breast cancers." (PMID 29541572, 2018). "In this study, Vitamin E (VE)-Albumin core-shell nanoparticles were developed for paclitaxel (PTX) delivery to improve the chemotherapy efficacy in an MDR breast cancer model." (PMID 30366367, 2018). "The present study fabricated the PTX loaded VE-Albumin core-shell nanoparticles to treat MDR breast cancer." (PMID 30366367, 2018). "Similar treatment of a highly metastatic breast cancer model using human serum albumin-titanocene formulation significantly inhibited cancer growth." (PMID 29348537, 2018). "Doxorubicin- (DOX-) polyethylenimine (PEI) loaded in human serum albumin (HSA) nanoparticles was found to be showing good results to treat the breast cancer." (PMID 29862118, 2018). "Recently, researchers have developed albumin-based MnO2 NPs for pH-responsive MR imaging and enhanced radiotherapy of breast cancers." (PMID 29255705, 2017). "The analysis was conducted with complete datasets for 982 breast cancer patients, 2134 patients were excluded because of missing values, either calcium or albumin and 1994 patients were excluded due to missing mammograms." (PMID 28464481, 2017). "Our results showed that the delivery of copper nanoparticle with albumin nanocarrier, has an inhibitory effect on the viability of human breast cancer cell lines similar to the effect of naked copper nanoparticles." (PMID 29186208, 2017). "The value of nanoparticle albumin-bound paclitaxel (nab-paclitaxel) in neoadjuvant systemic therapy for breast cancer remains uncertain." (PMID 28061451, 2017). "An inverse association was observed between serum calcium levels, adjusted to serum albumin levels, and percentage mammographic density in patients with primary breast cancer." (PMID 28464481, 2017). "Novel phantom models were produced, by adding perchloric acid extracts of either metastatic mouse breast carcinoma cells or healthy mouse brain to bovine serum albumin." (PMID 27686882, 2016). "Albumin nanoparticles containing the established chemotherapeutic, paclitaxel (marketed under the name Abraxane®), have been approved for the treatment of breast cancer, pancreatic adenocarcinoma and non-small cell lung cancer." (PMID 25848850, 2015). "In the market, there is already an injectable formulation of PTX-albumin nanoparticles, known as Abraxane®, that has been used in the treatment of breast cancer." (PMID 26605001, 2015). "Nanoparticle albumin-bound paclitaxel (nab-paclitaxel) is currently approved in Japan for treatment of breast cancer." (PMID 25789050, 2015).
breast carcinoma (continued). "In fact, a nanoparticle formulation of paclitaxel in which serum albumin is included as a carrier (Abraxane) has been approved for the treatment of breast cancer." (PMID 24498272, 2014). "GPS is based on a combination of CRP and albumin and has been evaluated in a variety of cancers, such as renal cancer, breast cancer, non-small cell lung cancer, gastroesophageal cancer, pancreatic cancer, and colorectal cancer." (PMID 24885814, 2014). "Prior studies demonstrated that low serum ALB is an independent predictor of poor survival in several types of cancer including gastrointestinal cancer, lung cancer, ovarian cancer and breast cancer, as well as NPC." (PMID 24718309, 2014). "In vitro, the proliferation or growth of cancer cell lines (i.e., human breast cancer cell lines) is inhibited by high concentrations of albumin." (PMID 24718309, 2014). "Timely surgery followed by carboplatin and albumin-bound paclitaxel has achieved complete remission in one patient with tumor emboli and recurrent chondroid-metaplastic breast cancer." (PMID 25364575, 2014). "Nanoparticle albumin-bound paclitaxel treatment is a good option for patients with breast cancer with taxanes-related skin toxicity." (PMID 24386978, 2014). "Abraxane (the trade name of albumin-based nanoparticles) was approved in 2005 for the treatment of recurrent or metastatically advanced breast cancer." (PMID 24369011, 2013). "Blood samples were collected from 152 breast cancer patients before and after each cycle of doxorubicin chemotherapy to measure the serum levels of ischemia-modified albumin, cardiac troponin T and creatine kinase-MB." (PMID 24223946, 2013). "Cox regression analysis showed that ALB and TB levels and primary tumor and lymph node metastases were significantly correlated with the survival time of breast cancer patients with liver metastasis (P<0.05)." (PMID 23691457, 2012). "Using 125I-labeled serum albumin, we have assessed this fraction in fluid isolated by centrifugation from chemically induced mammary carcinomas in rats, another solid epithelial tumor." (PMID 21541282, 2011). "Prior studies have reported that lower serum albumin concentrations, elevated serum amyloid A concentrations, and elevated YKL-40 concentrations are all associated with poor breast cancer prognosis." (PMID 21639875, 2011). "Pretreatment of rosiglitazone (8 mg/kg) for five days before cisplatin (7.5 mg/kg) treatment showed significant decrease in BUN and creatinine levels and increased albumin levels as compared to cisplatin (7.5 mg/kg) treated rats in breast cancer animals." (PMID 19356226, 2009). "Liposomal doxorubicin is already an approved treatment for breast cancer; albumin nanoparticulate chaperones of paclitaxel were approved for locally recurrent and metastatic breast cancer in 2005." (PMID 19416503, 2009). "The relationship between albumin concentrations and outcome are therefore consistent with those previously reported in patients with advanced breast cancer." (PMID 17375036, 2007). "The aim of the present study was to examine the relationship between clinico-pathologic status, C-reactive protein and albumin concentrations, measured before surgery and cancer-specific survival in patients with invasive primary operable breast cancer." (PMID 17375036, 2007). "The extent of deprivation (Carstairs deprivation index) was directly associated with the magnitude of the systemic inflammatory response (reduced albumin and elevated C-reactive protein, P<0.01) in patients with primary operable breast cancer (n=314)." (PMID 15305191, 2004). "Albumin-encapsulated liposomes have emerged as a highly promising platform for delivering paclitaxel against breast cancer, combining the enhanced solubility and tumor-targeting features of nab-paclitaxel with the advantages of stability and controlled release of liposomal carriers." (PMID 41489768, 2026).